USP9Y (ubiquitin specific peptidase 9 Y-linked)
Description:
Deubiquitinase that mediates deubiquitination of target proteins. May stabilize target proteins that are important for male germ cell development.
Synonyms: DFFRY; FAF-Y; AZFA; SPGFY2; AZFAT1; NCRNA00138; TTTY15
Tractability: PROTAC: ubiquitination databases record sites on it; its protein half-life has been measured.
Gene: Protein-coding gene on chromosome Y (12,537,650 to 12,860,852, forward strand). Ensembl gene ENSG00000114374.
Subcellular location (Human Protein Atlas): Vesicles
Gene Ontology:
Molecular function: cysteine-type deubiquitinase activity; co-SMAD binding; cysteine-type peptidase activity
Biological process: BMP signaling pathway; cell migration; protein deubiquitination; spermatogenesis; transforming growth factor beta receptor signaling pathway; protein ubiquitination
Cellular component: cytoplasm
Homologues: Orthologues: chimpanzee USP9Y (96% identical), macaque USP9Y (96% identical), tropical clawed frog usp9x (88% identical), zebrafish usp9 (85% identical), rat Usp9y (83% identical), mouse Usp9y (83% identical). Paralogues in human: USP9X (92% identical), USP24 (12% identical), USP34 (9% identical), USP32 (8% identical), USP15 (8% identical), USP19 (8% identical), USP4 (8% identical), USP31 (7% identical), USP8 (7% identical), USP43 (7% identical), USP38 (7% identical), USP36 (7% identical), and 59 more.
Diseases named in the same sentence as USP9Y in open-access papers:
USP9Y is named in the same sentence as 27 diseases in open-access papers, as found by Europe PMC text mining. Sharing a sentence is not in itself a finding about the gene and the disease. The quoted sentences say what the papers report.
Azoospermia (31 papers, 2008 to 2025). Absence of any measurable level of sperm,whereby spermatozoa cannot be observed even after centrifugation of the semen pellet. "Recent studies on the genetics of azoospermia have identified specific genes associated with a large spectrum of testis phenotypes, from hypospermatogenesis (USP9Y) to residual spermatogenesis (PRY, RBBMY, BPY2, DAZ)." (PMID 38403804, 2024). "KDM5D is one of the AZFb region genes on Y-chromosome, similar to USP9Y, it has been linked to azoospermia and spermatogenic failure." (PMID 34190021, 2022). "Furthermore, USP9Y is linked to spermatogenic failure and azoospermia." (PMID 34190021, 2022). "The single deletion of USP9Y is related to a wide range of testicular phenotypes that range from azoospermia with insufficient spermatogenesis to normal spermatism." (PMID 35912115, 2022). "In humans, the isolated absence of USP9Y has been linked to a spectrum of phenotypes, ranging from azoospermia with hypospermatogenesis to severe oligozoospermia and normozoospermia." (PMID 40169970, 2025). "Expression of WT hUSP26 resulted in increased expression of Usp26, Usp9y, Dazl, and Dppa3, whereas induction of these genes by the azoospermia-associated USP26 L364F variant was not significantly different from control samples." (PMID 35857630, 2022). "The deletions of USP9Y have been associated with azoospermia or severe oligospermia, but it might not be essential for normal sperm production and fertility in humans." (PMID 31828149, 2019). "The gene USP9Y, located in the AZFa region, was considered a candidate male fertility gene, following the discovery of an inactivating mutation in a man with nonobstructive azoospermia, which was absent in his fertile brother." (PMID 21179482, 2010). "This study conduct on23 idiopathic azoospermia men and 5 fertile men as the control group for analyzing the DAZ, RBMY1, USP9Y, protamine-2, SRY, and actin gene expression." (PMID 33349804, 2020). "In this study, we identified an approximately 384.9 kb AZFa microdeletion in an azoospermia-affected patient, which specifically affects USP9Y without involving DDX3Y, alongside a homozygous CFTR variant." (PMID 40169970, 2025).
infertile (20 papers, 2007 to 2025). "The deletions in the region of the linked gene USP9Y are highly associated with infertility associated with oligospermia and azoospermia." (PMID 35910557, 2022). "USP9Y is localized in a region of the Y chromosome known to be associated with infertility (AZFa)." (PMID 28747152, 2017). "We also generated an animal model of the AZoospermia Factor a (AZFa) deletion, encompassing Usp9y, Uty, and Ddx3y, which in men causes the most severe form of infertility characterized by a complete absence of germ cells." (PMID 39847625, 2025). "Therefore, USP9Y has been considered a key gene for screening the Y chromosome for microdeletions in infertile or subfertile men." (PMID 35910557, 2022). "Located in the AZFa region is Ubiquitin specific peptidase 9 Y linked (USP9Y), which plays an important role in male reproductive development and spermatogenesis, as studies have shown its absence in infertile men whilst also noting its lack even in normal sperm count fertile men." (PMID 36405559, 2022). "Our findings implicate Y-chromosomal genes, including USP9Y, UTY, TXLNGY, RBMY1B, RBMY1E, RBMY1J and TSPY4, some of which are known to be important for spermatogenesis, in the curative hormonal treatment of cryptorchidism-induced infertility." (PMID 31171972, 2019). "Although USP9Y and DBY deletions alone are not considered to be the major causes of infertility, but construed to be fine tuners of the process of normal spermatogenesis along with other key players." (PMID 22844483, 2012). "We observed deletions of the USP9Y and DBY genes in the infertile patients with normal spermiogram." (PMID 22844483, 2012).
male infertility (16 papers, 2007 to 2025). The inability of the male to effect fertilization of an ovum after a specified period of unprotected intercourse. "The Usp9y gene discovered by RIT is associated with male infertility and Sertoli cell-only syndrome." (PMID 17490475, 2007). "This included Usp26 itself, Dazl, which encodes an RNA-binding protein that is essential for gametogenesis in both males and females, Usp9y, a Y-linked gene encoding a deubiquitylase associated with male infertility and Dppa3, a primordial germ cell (PGC)-specific protein." (PMID 35857630, 2022). "Loss of the human USP9Y gene did not cause male infertility, suggesting that USP9Y is not the causative gene." (PMID 39551844, 2024).
prostate carcinoma (7 papers, 2016 to 2025). A carcinoma that arises from epithelial cells of the prostate gland. "Additionally, we identified key genes co-expressed with UTY and USP9Y, offering insights into potential therapeutic targets for bone metastasis in prostate cancer." (PMID 40299503, 2025). "Through pseudo-time analysis, we traced the dynamic trajectory of tumor cells from primary prostate cancer to bone metastasis, highlighting the crucial role of UTY and USP9Y in this process." (PMID 40299503, 2025). "Additionally, a study of prostate cancer in Asian populations found several novel fusions involving lncRNAs, including a surprisingly common gene fusion between the USP9Y protease and the TTTY15 ncRNA, which results in a fusion transcript and is associated with a loss of USP9Y function." (PMID 27105842, 2016). "Some studies have shown that a fusion of the TTTY15 gene with USP9Y (TTTY15–USP9Y) predicts prostate biopsy results in multiple cases of hepatocellular carcinoma, lung cancer, and prostate cancer, suggesting that TTTY15-USP9Y fusion is a potential driver of carcinogenesis." (PMID 31311130, 2019). "To assess the downstream effects of knocking down USP9X and USP9Y on a transcriptome-wide scale, we have conducted microarray profiling experiments using the human DU145 prostate cancer cell culture model, after confirming the robust expression of both USP9X and USP9Y in this model." (PMID 31294067, 2019).
Sertoli Cell-Only Syndrome (7 papers, 2006 to 2025). A type of male infertility in which no germ cells are visible in any of the biopsied SEMINIFEROUS TUBULES (type I) or in which germ cells are present in a minority of tubules (type II). "Secondly, three IR-rich genes (USP9Y, DDX3Y, DAZ1), or their protein products, play a significant role in Sertoli cell-only syndrome (DOID:0050457)." (PMID 41155472, 2025).
heart failure (4 papers, 2018 to 2024). Inability of the heart to pump blood at an adequate rate to meet tissue metabolic requirements. "An expression profiling study based on new-onset heart failures caused by idiopathic dilated cardiomyopathy demonstrated that USP9Y, DDX3Y, RPS4Y1, and EIF1AY were significantly upregulated in male patients with high-fold changes." (PMID 29361784, 2018). "Our study also identified the importance of USP9Y, a male-specific transcript, previously found to be overexpressed in myocardial samples with heart failure." (PMID 39198331, 2024). "In addition, an expression profiling study based on new-onset heart failures demonstrated that DDX3Y, EIF1AY, and USP9Y are upregulated in male subjects." (PMID 36831031, 2023).
coronary artery disease (2 papers, 2018). "This region is reportedly associated with coronary artery disease, and the up-regulation of specific genes within it (namely EIF1AY and USP9Y, as found in cc2) specifically linked with idiopathic heart failure." (PMID 29971234, 2018). "Polymorphisms in the USP9Y gene affect serum lipid profiles and coronary heart disease risk, showing that this Y-linked gene has a non-gametogenesis function." (PMID 29335024, 2018).
hepatocellular carcinoma (2 papers, 2017 to 2019). A malignant tumor that arises from hepatocytes. "This study provides the first evidence of the expression of Y-linked lincRNA transcripts such as lnc-KDM5D-4:1, lnc-ZFY-1:1, lnc-ZFY-2:1, lnc-RBMY1B-1:1, lnc-RBMY1B-1:4, lnc-USP9Y-1:4, and lnc-HSFY2-3:6 in human hepatocellular carcinoma (HCC)." (PMID 29196750, 2017).
lung carcinoma (2 papers, 2019 to 2025). "While USP9Y overexpression has been shown to inhibit lung cancer tumorigenesis, USP9Y fusion to TTTY15 appears to be a common event in prostate tumors of Chinese ancestral patients, suggesting a possible mechanism for PDV functionality through altering USP9Y expression or TTTY15 fusion." (PMID 40454088, 2025). "Recent work has also found that DDX3Y is stabilized by USP9Y, and tumor suppressive effects were observed in lung cancer cells when both DDX3Y and USP9Y were overexpressed." (PMID 40454088, 2025).
adenoma (1 paper, 2020). A neoplasm arising from the epithelium. "Several of these genes, e.g., EIF1AY, USP9Y, ZFY, TMSB4Y, have been used as gender-specific tissue biomarkers for both normal and tumoural tissues; corticotrope adenomas can now be added to the list of tissues presenting these markers of sexual dimorphism." (PMID 32183012, 2020).
Alzheimer disease (1 paper, 2024). A progressive, neurodegenerative disease characterized by loss of function and death of nerve cells in several areas of the brain leading to loss of cognitive function such as memory and language. "Additionally, USP9Y displays significant gender-linked expression in the adult brain and shows diminished expression in Alzheimer’s disease." (PMID 39449082, 2024).
atherosclerosis (1 paper, 2023). A disease characterized by the build-up of fatty material and calcium deposition in the arterial wall resulting in partial or complete occlusion of the arterial lumen. "The present study identifies genes already classified in the atherosclerosis process as genes that codify for encoding cellular adhesion molecules (NLGN4Y), cellular exocytosis (TXLNGY), induction of IFN-α (DDX3Y), cellular apoptosis (EF1AY), and prevention of protein degradation (USP9Y)." (PMID 36831031, 2023).
autism (1 paper, 2022). Persistent deficits in social interaction and communication and interaction as well as a markedly restricted repertoire of activity and interest as well as repetitive patterns of behavior. "The Simons Foundation Autism Research Initiative (SFARI) [geneSFARI.org] lists four genes of Y chromosome associated with autism vizNLGN4Y, ASMT, USP9Y,andSHOX." (PMID 35169779, 2022).
major depressive disorder (1 paper, 2024). An episode of depression lasting two or more weeks without an intervening episode of mania. "Furthermore, male mice also express USP9Y, and there is evidence suggesting that USP9Y, along with seven other genes, is among the commonly differentially expressed genes in the dorsolateral prefrontal cortex of subjects with AD or major depressive disorder." (PMID 39449082, 2024).
cancer (8 papers, 2017 to 2025). A tumor composed of atypical neoplastic, often pleomorphic cells that invade other tissues. "Some studies revealed that the fusion of the TTTY15 gene with USP9Y (Ubiquitin Specific Peptidase 9 Y-linked) gene is a potential carcinogen in some cancers particularly in PCa." (PMID 33349800, 2020). "DUBs are critical key players in diverse processes such as (i) spermatogenesis (e.g. USP2, USP8, USP9y, USP14, USP26, Uchl-1, Uchl-3 and CYLD), (ii) cancer biology (e.g. USP7, USP10 and USP11), and (iii) stemness and differentiation (e.g. USP7, USP9x, USP22, USP44 and Psmd14)." (PMID 28659380, 2017).
tumor (7 papers, 2013 to 2025). "Second, in vitro functional studies, particularly under androgen deprivation therapy (ADT) conditions, can clarify how UTY or USP9Y loss affects tumor cell proliferation, apoptosis, invasion, and organoid-forming capacity." (PMID 40299503, 2025). "In addition, our study identified two Y chromosome-linked genes, UTY and USP9Y, which are highly expressed in PCa bone metastases and are strongly associated with tumor cell proliferation, metastasis, and immune evasion." (PMID 40299503, 2025). "Some authors have reported that ubiquitin specific peptidase 9, Y-linked (USP9Y)–TTTY15 is expressed in both tumor and nonmalignant samples and can be used to predict the outcome of a prostate biopsy." (PMID 31311130, 2019). "Most of these genes (MUC12, S100P, GSTT1, USP9Y, MSLN and so on) are involved in tumor initiation, progression or metastasis." (PMID 23787019, 2013).
USP9Y also shares sentences with these, for which no sentence is quoted: spermatogenic failure (5 papers); gastric cancer (3); cryptorchidism (2); idiopathic dilated cardiomyopathy (2); Klinefelter syndrome (2); non-small cell lung carcinoma (2); oligospermia (2); cardiovascular diseases (1); hydrocele (1); prostate tumor (1); varicocele (1).